INS (insulin)
Diseases named in the same sentence as INS in open-access papers (continued):
Sharing a sentence is not in itself a finding about the gene and the disease.
cardiac hypertrophy (continued). "Deletion or inhibition of CPT-1β can lead to the inhibition of fatty acid oxidation, myocardial lipid accumulation, impaired insulin sensitivity, heart regeneration, cardiac hypertrophy, cardiac fibrosis, and cardiac dysfunction in mice." (PMID 39338366, 2024). "Histological analysis indicated that myocardial hypertrophy, the fibrosis area, and extracellular matrix deposition in the heart in the diabetic group were improved after insulin and Rb1 treatment." (PMID 38961333, 2024). "Accordingly, the combinatorial GR+KLF15 knockdown blocked the treatment effects on diastolic dysfunction (E/e′), stroke volume, cardiac hypertrophy (heart weight/tibia length), and insulin-driven glucose uptake." (PMID 39378111, 2024). "Deletion or inhibition of CPT-1β can lead to myocardial lipid accumulation, reduced insulin sensitivity, cardiac hypertrophy, cardiac fibrosis, and cardiac dysfunction in mice." (PMID 39338366, 2024). "Both propionate and butyrate increased plasma incretins and insulin sensitivity, and acetate enhanced cardiac hypertrophy, insulin sensitivity, and oxidative stress, and elevated plasma HDLc levels." (PMID 36904067, 2023). "The transcriptome changes predicted increased cardiac hypertrophy and activation of insulin and phosphoinositide signaling pathways in the 7d-MI + 21 group compared to the 1d-MI + 21 group." (PMID 37009793, 2023). "We are the first group to report the predicted mechanism of how metformin reverses the cardio-detrimental effects of miR-7-5p via activation of target genes which are involved in insulin signaling, inflammation, fibrosis, and cardiac hypertrophy." (PMID 37569355, 2023). "Abnormal BCAA metabolism can lead to myocardial hypertrophy through insulin resistance, and ventricular remodeling due to myocardial hypertrophy can induce heart failure." (PMID 35911554, 2022). "Insulin has the role of anabolic hormone and acts as cardiac growth factor, promoting cardiac hypertrophy due to the interaction with its receptors on heart muscle cells." (PMID 35135591, 2022). "A possible correlation is supported by the close temporal relationship between cardiac hypertrophy and insulin infusion, and its resolution after suspension of insulin therapy." (PMID 35135591, 2022). "In the heart, there has been a focus on the effects of insulin to increase protein synthesis because it is a key feature of cardiac hypertrophy." (PMID 35766350, 2022). "In the majority of cases, cardiac hypertrophy due to a hyperinsulinemic condition is asymptomatic and reversible after the normalization of insulin levels." (PMID 35135591, 2022). "A lack of ACADL resulted in the accumulation of diacylglycerol, liver insulin resistance, and myocardial hypertrophy." (PMID 34638602, 2021). "Although insulin-induced cardiac hypertrophy is reported, very little information is available on the hypertrophic effect of insulin on ventricular cardiomyocytes and the regulation of sodium and calcium homeostasis." (PMID 34835942, 2021). "Given the important roles of class II HDACs in the pathogenesis of cardiac hypertrophy and for the maintenance of insulin sensitivity and energy balance, these enzymes will be a potential target for drug development or disease control in the future." (PMID 32770227, 2020). "In contrast, constitutive PKD activation prevents cardiac insulin resistance and mitigates against obesity-induced cardiac hypertrophy, despite inducing hypertrophy in lean animals." (PMID 33099046, 2020). "Optimizing cardiac energy production in the failing heart via improving cardiac insulin signalling is cardioprotective against cardiac dysfunction and hypertrophy." (PMID 30626440, 2019). "As discussed in the introduction, it is well known that high insulin levels elevate blood pressure, promote myocardial hypertrophy and increase sodium retention by the kidney." (PMID 31357547, 2019).
cardiac hypertrophy (continued). "This suggests that myocardial insulin resistance and mitochondrial dysfunction play important roles in the ventricular remodeling and systolic dysfunction that occur in cardiac hypertrophy." (PMID 31461405, 2019). "Several studies demonstrate the protective effects of adiponectin, an adipocyte-secreted hormone with anti-inflammatory and insulin-sensitizing effects, on cardiac hypertrophy and fibrosis." (PMID 31842996, 2019). "Insulin/IGF1 and HIF1α are the components of key signaling mechanisms that regulate ROS levels associated with aging and cardiac hypertrophy and failure." (PMID 31511561, 2019). "There is consensus that prolonged cardiac exposure to excess circulating fuels (e.g., glucose, FFAs, and triglycerides) and growth hormones (e.g., insulin and leptin) speed up myocardial pathology that leads to cardiac hypertrophy and failure." (PMID 30344301, 2018). "The heart condition defined as lipotoxic cardiomyopathy is characterized by cardiac hypertrophy, ectopic lipid accumulation, and insulin resistance." (PMID 30485307, 2018). "Some of the other top drugs in the cardiac hypertrophy network were Insulin Human, Insulin Lispro, and Insulin Pork." (PMID 30514363, 2018). "A recent study showed that excessive activation of the insulin signaling pathway contributes to the development of pathologic cardiac hypertrophy." (PMID 27512079, 2016). "During pathological cardiac hypertrophy, the heart develops insulin resistance, resulting in a slower rate of glucose entry in response to insulin and a decrease in the capacity for glucose oxidation, without changes in the expression of GLUT4 transporters." (PMID 25376904, 2014). "Others are the direct action of increased levels of insulin on the myocytes of the heart resulting in cardiac hypertrophy and remodeling, the promotion of the growth of vascular smooth muscle cells and lipotoxicity." (PMID 24705608, 2014). "Cardiac hypertrophy is characterized by alterations in both cardiac bioenergetics and insulin sensitivity." (PMID 25376904, 2014). "CT-1 has been shown to promote cardiac hypertrophy, but also potentially restore insulin responsiveness." (PMID 23690661, 2013). "A crucial role in the pathogenesis of myocardial hypertrophy has been identified for insulin-related cell signaling pathways including the insulin/PI3k/PKB/Akt axis." (PMID 23226508, 2012). "In accordance, investigations in animal models have shown that exogenous insulin supply induces myocardial hypertrophy and interstitial fibrosis by activation of key mitogenic signaling pathways including angiotensin, MAPK-ERK1/2 and S6K1." (PMID 23226508, 2012). "Similarly, increased level of Klotho and inhibition of insulin/IGF1/AKT axis was related to abolished myocardial hypertrophy and fibrosis in mice." (PMID 37985893, 2023). "Moreover, the direction of insulin signaling is opposite that observed in models of pressure overload-induced cardiac hypertrophy and failure, which are characterized by increased IR/Akt-mediated signaling." (PMID 36125265, 2022). "The role of insulin in programming a cardiac phenotype as a primary outcome is supported in mouse studies by links between maternal hyperinsulinaemia resulting from maternal obesity, and offspring cardiac hypertrophy in the young adult." (PMID 35258482, 2022). "Furthermore, forkhead transcription factor Foxo3a-mediated transcriptional regulation of catalase inhibits cardiac hypertrophy by modulating ROS generation induced by insulin." (PMID 34439471, 2021). "During hypertrophic stress, increased C/EBPβ downregulates the mir15a/mir16‐1 cluster, resulting in up‐regulation of multiple target proteins (INSR, IGF1R, AKT3, SGK1) in cardiomyocytes, causing increased activation of insulin/IGF1 signaling, ultimately causing cardiac hypertrophy and dysfunction." (PMID 33377640, 2020). "These top drugs were all related with insulin and indicated insulin maybe play an essential role in cardiac hypertrophy." (PMID 30514363, 2018).
cardiac hypertrophy (continued). "In addition, other candidate drugs, such as Insulin Human, Insulin Lispro, and Insulin Pork which were all investigational or approved insulin-related drugs, were identified in our analysis as drug repurposing candidates for cardiac hypertrophy." (PMID 30514363, 2018). "Cardiac hypertrophy and enhanced contractility of the hyperinsulinemic monkeys might be attributed to myocardial adaptive responses to increased insulin stimulation." (PMID 29789568, 2018). "However, a recent study showed that insulin signaling actually contributes to the development of pathological cardiac hypertrophy." (PMID 27512079, 2016). "Molecular markers of insulin signaling and cardiac hypertrophy were analyzed." (PMID 27328820, 2016). "Thus, deciphering the crosstalk between the IGF-1 and insulin signaling pathways will be crucial to understanding the role of IR in exercise-induced cardiac hypertrophy." (PMID 27148064, 2016). "In diabetic heart, ventricular hypertrophy, metabolic abnormalities, extracellular matrix remodelling, fibrosis, vascular changes, insulin resistance, oxidative stress and apoptosis are the most important changes that may affect the myocardial function." (PMID 26886092, 2016). "A local elevation of BCAA concentrations may lead to chronic induction of mTOR, promoting cardiac hypertrophy by altering insulin sensitivity." (PMID 26267065, 2015). "High glucose and insulin levels have been demonstrated to promote cardiac hypertrophy." (PMID 23690661, 2013). "Furthermore, excess insulin signaling contributes to cardiac hypertrophy and dysfunction." (PMID 26064981, 2015). "Importantly, the authors showed that both glucose- and insulin-induced myocardial hypertrophy might be mediated by CT-1, suggesting that CT-1 expression could be directly increased by insulin and glucose stimulations." (PMID 23690661, 2013). "This study in male SD rats showed that swimming, as moderate intensity aerobic exercise for 8 weeks can reverse insulin resistance, reduce FBG levels, alleviate cardiac hypertrophy and myocardial fibrosis." (PMID 39250437, 2024). "The present study extends this cardiac hypertrophy to a specific population in which patients with concomitant HFrEF and T2DM are prescribed insulin." (PMID 37542280, 2023). "We combine in vivo and in vitro studies to demonstrate that miR15a/mir16‐1 represses insulin/IGF1 signaling, preventing cardiac hypertrophy and dysfunction development." (PMID 33377640, 2020). "We found that insulin-induced decreases in fatty acid oxidation were greater in the AAC group, further linking cardiac hypertrophy to myocardial insulin resistance." (PMID 31461405, 2019). "As noted, both PE and insulin activate mTORC1 signaling in ARVC, and mTORC1 also plays a key role in cardiac hypertrophy." (PMID 27512079, 2016). "Given the distinct signaling pathways activated α-adrenergic stimulation and insulin in ARVC, and their roles in cardiac hypertrophy, it was therefore important to compare the impact on the synthesis of specific proteins in ARVC." (PMID 27512079, 2016). "The roles of cardiac glucose uptake and insulin action have been demonstrated in mice with cardiac-specific ablation of GLUT4, which developed cardiac hypertrophy resembling that of the diabetic heart." (PMID 22992429, 2012). "Furthermore, GLP-1 analogs improved plasma insulin levels, HOMA-IR, cholesterol levels, and markers of liver damage (AST and ALT), as well as reduced liver hypertrophy." (PMID 41723268, 2026). "The cross-talk between insulin and IGF1 signaling also contributes to physiological cardiac hypertrophy, with defects in IGF1 signaling exacerbating exercise-induced hypertrophy, as evidenced by studies on mice with cardiomyocyte-specific deletions of IGF1R and IRS." (PMID 39125938, 2024).
cardiac hypertrophy (continued). "Additionally, it promotes insulin sensitivity through the activation of liver AMP-activated protein kinase (AMPK), prevents arteriosclerosis, exhibits anti-inflammatory effects, and suppresses myocardial hypertrophy." (PMID 38957872, 2024). "Thus, our results highly suggest that, as in vascular disease, an insulin-induced decrease in cardiomyocytes CREB levels could be responsible, at least in part, for the development of cardiac hypertrophy in diabetic patients." (PMID 34835942, 2021). "As anabolic hormones, insulin and IGF1 promote cardiac growth, playing a major role in coupling nutritional status to cell size rather than necessarily contributing to cardiac hypertrophy." (PMID 35766350, 2022). "Phosphorylation of GSK3α/β in response to insulin or IGF1 in the heart and cardiomyocytes is well-documented, although the emphasis is generally on its role in cardiac hypertrophy, rather than regulation of glycogen synthesis." (PMID 35766350, 2022). "Despite similar weight gain and increase in fasting blood glucose and insulin, only WT-HFHS but not KO-HFHS mice developed concentric cardiac hypertrophy and elevated left ventricular filling pressure." (PMID 34849611, 2022).
endometrial cancer (119 papers, 2003 to 2025). Primary or metastatic malignant neoplasm involving the endometrium (mucous membrane that lines the endometrial cavity). "Coffee consumption, particularly filtered varieties rich in chlorogenic acid, has been linked to 20–35% decreases in endometrial cancer risk through antioxidant, anti-inflammatory, and insulin-sensitizing actions." (PMID 41301707, 2025). "Conversely, weight loss, by reducing adiposity and the aromatase-induced conversion of androgens into oestrogen, improving insulin sensitivity and lowering the levels of inflammation, is associated with a reduction in the endometrial cancer risk." (PMID 38473385, 2024). "Increased serum insulin has been reported to be associated with roughly a doubling of endometrial cancer risk in postmenopausal women." (PMID 35530326, 2022). "A previous meta-analysis of observational studies similarly reported a higher endometrial cancer risk in women with raised fasting insulin." (PMID 36558416, 2022). "Our systematic evaluation of 14 previously reported candidate mediators of the effect of BMI on endometrial cancer risk identifies fasting insulin, bioavailable testosterone and SHBG as plausible mediators of this relationship." (PMID 35436960, 2022). "Several investigations reported an association between high levels of Ki-67, insulin, and glucose, and a poor prognosis in endometrial cancer." (PMID 33917520, 2021). "There is evidence for a direct effect on endometrial cancer cells of insulin and IGF-1; activation of the insulin receptor causes an increase in cell proliferation and inhibition of apoptosis through both the MAPK and PI3K/Akt pathways." (PMID 34359595, 2021). "Epidemiological studies have shed insights into a possible mechanistic link between insulin and the risk of endometrial cancer 24, which includes sex steroid hormones, adipokines, and low‐grade inflammation." (PMID 29533014, 2018). "We extend these findings by demonstrating that insulin was an independent predictor of LNM risk in endometrial cancer for both premenopausal and postmenopausal Chinese women." (PMID 29533014, 2018). "High saturated fat consumers were reported to suffer from reduced insulin sensitivity, which is a risk factor of endometrial cancer." (PMID 29283380, 2017). "For the first half-year of cumulative treatment time on insulin glargine relative to that on human insulin, we found an increased risk for colorectal and any cancer in women and both sexes combined, and for endometrial cancer in women." (PMID 28573394, 2017). "For example, among postmenopausal nonusers of hormone therapy, women who were classified in the highest versus lowest quartile of insulin levels had a 2.3-fold increased risk of developing endometrioid-type endometrial cancer." (PMID 27125830, 2016). "We observed an association of variants associated with higher fasting insulin with higher risk of endometrial cancer (odds ratio [OR] per genetically predicted SD of log-FI = 2.34, 95% confidence interval [CI] = 1.06 to 5.14, P = .03)." (PMID 26134033, 2015). "Genetically predicted higher fasting insulin levels were associated with greater risk of endometrial cancer (odds ratio [OR] per standard deviation = 2.34, 95% confidence internal [CI] = 1.06 to 5.14, P = .03)." (PMID 26134033, 2015). "We found a directionally consistent association of genetically predicted higher postchallenge insulin levels with a higher risk of endometrial cancer (OR = 1.40, 95% CI = 1.12 to 1.76, P = .003)." (PMID 26134033, 2015). "In conclusion, this study provides evidence for a causal role of higher insulin levels in the etiology of endometrial cancer." (PMID 26134033, 2015). "One major mechanism is that adiponectin can decrease blood insulin levels, and therefore can inhibit cancer development, as the insulin-upregulated estrogen is one of the predominant risk factor for endometrial cancer." (PMID 26030130, 2015).